TERT (telomerase reverse transcriptase)
Diseases named in the same sentence as TERT in open-access papers (continued):
Sharing a sentence is not in itself a finding about the gene and the disease.
melanoma (continued). "On the other hand, it is interesting to note that TERT promoter mutation is an independent prognostic marker in other cancers (e.g., melanoma, thyroid cancer, urothelial carcinoma) and is not influenced by other mutations such as RAS or BRAF mutations." (PMID 32957941, 2020). "However, the result showed that only male melanoma patients in the TERT altered group had longer median OS than unaltered group (49 months vs 27 months, p<0.001)." (PMID 32915164, 2020). "TERT promoter mutations are present in melanoma; however, it is not yet known how they function to promote melanoma." (PMID 33024276, 2020). "The selection of mutational targets for ctDNA analysis was based on the following criteria: (a) known melanoma hotspot mutation in BRAF, NRAS, and/or TERT promoter; (b) COSMIC/TCGA reported mutation; (c) other mutation with a polyPhen score >0.7 and high variant allele frequency (VAF) in the tumor." (PMID 30312528, 2019). "A series of 105 advanced melanoma patients were analysed by TERT promoter Sanger sequencing." (PMID 30934988, 2019). "Several authors have reported a prognostic significance of TERT promoter mutations in primary melanomas, whereas other studies found no impact in primary and metastatic melanoma." (PMID 30934988, 2019). "Currently, the National Comprehensive Cancer Network (NCCN) reports that BAP1 testing may be warranted in specific cases, along with testing for other melanoma-predisposing genes like CDK4, MITF and TERT." (PMID 31382929, 2019). "Of note, it has been reported that melanoma cells harbor a subset of critically short telomeres and that the upregulation of telomerase activity associated with TERT promoter mutations does not preclude telomere attrition." (PMID 29695835, 2018). "Clinically, BRAF or NRAS-mutant melanoma patients whose tumors have TERT promoter mutations have poor overall survival compared to patients with tumors with a non-mutated TERT promoter." (PMID 29695835, 2018). "Previously, we have shown that the TERT promoter mutations associated with poor survival in patients with primary melanoma and our subsequent data showed shorter telomeres in tumors with than without the TERT promoter mutations." (PMID 30026606, 2018). "Interestingly, the TERT gene is located only 600 kb away from IRX4 and is now considered as a major player of melanoma predisposition." (PMID 29963229, 2018). "Moreover, comparison of the porcine results to those reported by human melanoma GWAS indicated shared association signals notably at CDKAL1 and TERT loci but also nearby CCND1, FTO, PLA2G6 and TMEM38B-RAD23B loci." (PMID 29963229, 2018). "In melanoma, coexistence of BRAF V600E and TERT promoter mutations was associated with increased tumor thickness, high mitotic rate, lymph node metastasis, presence of ulceration, absence of regression, high risk of tumor recurrence, and melanoma-specific mortality." (PMID 29422527, 2018). "Our study uncovers a robust dependency of NRAS-mutant melanoma on TERT, and provides proof-of-principle for a new combination strategy to combat this class of tumors, which could be expanded to other tumor types." (PMID 29695835, 2018). "We found that both TERT depletion or treatment with 6-thio-dG upregulated ROS, and that TERT can potentiate the antioxidant capacity of melanoma cells in a RT and telomere length-independent manner, enabling melanoma cells to survive under conditions of excessive oxidative stress." (PMID 29695835, 2018). "In addition, UV-related mutations along with hot spot mutations have also been identified in the promoter region of telomerase (TERT) gene in sun-exposed tumours such as melanoma, basal cell carcinoma, non melanoma skin cancer and conjunctiva SCC." (PMID 29562930, 2018).
melanoma (continued). "In some of the conventional AYA melanoma cases studied here, the TERT promoter was neither mutated nor hypermethylated." (PMID 28378855, 2017). "Given the high prevalence of the TERT promoter mutations C228T and C250T in cutaneous melanoma, their addition to existing tests for detection of mutant BRAF and NRAS will allow monitoring of most melanoma patients using ddPCR." (PMID 29108273, 2017). "It did not however correlate with cell proliferation (Ki-67 immunostaining), nor differ significantly in prevalence between primary melanomas with or without a TERT promoter mutation." (PMID 29262649, 2017). "In summary, we report strong ETS1 expression in all nevi and melanomas but not normal melanocytes, providing a mechanism for how early TERT promoter mutations can be selective following oncogene activation." (PMID 29262649, 2017). "TERT promoter mutations were more frequent in non-acral skin melanomas (50%) than in mucosal (23%) and acral (19%) melanomas." (PMID 29156643, 2017). "In addition, telomere-related loci have been associated with risk of melanoma in GWAS including: ATM, TERT, and more recently, OBFC1." (PMID 28212542, 2017). "The other mutated case was an acral melanoma diagnosed in 2009, displayed a -124:G>A TERT promoter mutation, but not a BRAF mutation; the patient died 24 months after diagnosis, in line with the poor prognosis of CM harbouring TERT promoter mutations." (PMID 28662141, 2017). "Our results indicate that ZNF148 may regulate TERT expression in pancreatic, testicular, lung, and melanoma tumour cell lines via a regulatory element that is disrupted by the G allele at rs36115365." (PMID 28447668, 2017). "ETS1 is reported to be important for TERT upregulation in melanoma." (PMID 29262649, 2017). "TERT mRNA levels were also significantly higher in melanomas harboring TERT promoter mutation and/or methylation than in those without these alterations." (PMID 28378855, 2017). "To investigate a link between MAPK pathway activation and TERT expression in presence or absence of TERT promoter mutation, we performed experiments on nine melanoma cell lines with or without TERT, BRAF and NRAS mutations." (PMID 27449293, 2016). "The UK family with the promoter variant was identified came from a series of 139 three-or-more case melanoma families, of which 56 (40 %) have a CDKN2A mutation; 2 (1.4 %) have a CDK4 mutation, 4 (2.8 %) have shelterin mutations, and now 1 (0.7 %) has a TERT promoter mutation." (PMID 26433962, 2016). "This has been previously shown to be true in melanoma, in which TERT mutations are associated with different histology types of the disease, and are more commonly found in melanoma without regression as compared to melanoma with regression." (PMID 27792139, 2016). "Since the original reports in melanoma, we have found some published work that suggests TERT promoter mutations are absent in DLBCL and CLL." (PMID 27792139, 2016). "Although the real role of POT1 in melanoma – as for TERT – needs to be fully understood, all these findings suggest that genes involved in telomere maintenance may contribute to the disease pathogenesis." (PMID 26322273, 2015). "The telomere-associated SNPs in TERC, TERT, OBFC1, and RTEL1 are near (8-150kb from) SNPs strongly associated with melanoma risk (rs12696304 in TERC, P = .0001; rs455433 in TERT, P = 2.26x10-16; rs2995264 in OBFC1, P = 7.10x10-6; rs75691080 in RTEL1, P = 1.02x10-6) (available online)." (PMID 25231748, 2014). "Accordingly, we now propose a revised genetic model of melanoma progression, in which immortalization with TERT expression is not required for melanoma initiation as previously proposed but is associated more with progression." (PMID 21418545, 2011). "However, how telomerase activity influences melanoma cell doubling time remains unclear, and the pathways linking TERT expression to faster cell-cycle progression require further study." (PMID 41744838, 2026).
melanoma (continued). "A study analyzing 95 melanoma patients treated with ICIs found that genes affected by VARs associated with hypophysitis include SMAD3, PRDM1, and IL1RN, while genes affected by CNVs related to the occurrence of hypophysitis are TERT, SMAD3, JAK2, PRDM1, FAN1, CD274, and UNG." (PMID 41465179, 2025). "Likewise, TERT promoter mutations are associated with aggressive disease features, such as increased recurrence risk and disease-specific mortality in PTC, as well as greater malignant potential in melanoma, glioma, and urothelial cancers." (PMID 40469184, 2025). "Our study evaluated whether there are statistically significant differences between TERT immunohistochemistry expression in melanocytic nevi and thin melanomas regarding the percentage, intensity, and localisation of the staining or whether it is associated with other clinicopathological variables." (PMID 40361989, 2025). "Consequently, TERT inhibition represents a promising therapeutic strategy for melanoma." (PMID 40737104, 2025). "A subsequent German clinical trial on patients with melanoma demonstrated that BRAF/MEK inhibitors could induce much superior therapeutic responses in patients harboring a coexisting BRAF mutation and TERT promoter mutation compared with patients harboring only a BRAF mutation." (PMID 38735658, 2024). "In addition, we found that the level of TERT methylation could potentially serve as a predictive biomarker for immunotherapy in patients with mucosal melanoma." (PMID 38695555, 2024). "Finally, we demonstrated that inhibition of the telomere lengthening function of TERT reduced the proliferation of parental and resistant melanoma cells when cells were grown in 2D or as spheres known to be enriched in cells with characteristics of tumor-initiated cells." (PMID 37296851, 2023). "Although the association between TERT expression and the PFS could not be directly assessed in this small cohort, these results suggest that the high expression level of TERT might be involved in resistance to BRAF and MEK inhibitors in patients with BRAF-mutated melanomas." (PMID 37296851, 2023). "Telomerase reverse transcriptase (TERT) promoter mutations occur frequently in cancer, have been associated with increased TERT expression and cell proliferation, and could potentially influence therapeutic regimens for melanoma." (PMID 37418389, 2023). "However, mucosal melanomas tend to differ from their cutaneous counterparts in terms of molecular profiling; albeit showing a heterogeneous molecular profile, they have lower BRAF and TERT, and relatively higher NRAS and KIT mutation frequencies." (PMID 35642348, 2023). "Here, we test if TERT promoter mutations and TERT expression are associated with OS and progression free survival (PFS) under ICI, as well as clinicopathological and demographic parameters in multiple highly annotated melanoma cohorts with exome- and transcriptome sequencing." (PMID 37418389, 2023). "Therefore, in TERT-high hypoxic melanoma, dysfunctional CD4+ T cells may accumulate employing these immuno-suppressive checkpoints." (PMID 37418389, 2023). "These accumulating mutations include TERT (telomerase reverse transcriptase) promoter mutations, components of the SWI/SNF (switch/sucrose non-fermentable or BAF) chromatin remodeling complex and loss of CDKN2A which are early events noted along the trajectory of nevus to melanoma transition." (PMID 36834954, 2023). "Some investigations have reported mutually exclusive patterns, suggesting that TERT promoter mutations may represent an alternative pathway of telomerase activation in melanoma cases lacking BRAF or NRAS mutations." (PMID 37504268, 2023). "In addition, our data indicate dysfunctional CD4+ T cells in TERT high hypoxic melanoma." (PMID 37418389, 2023).
melanoma (continued). "Four dermatopathologists reviewed the histology of melanomas from individuals with germline variants in POT1 (n = 30 melanomas, 17 individuals), TERF2IP (n = 4 melanomas, 3 individuals), ACD (n = 4 melanomas, 2 individuals), and TERT (n = 2 melanomas, 2 individuals)." (PMID 36876055, 2023). "A study based on 1469 melanoma patients and 1158 healthy controls showed a statistical association between increased telomere length and melanoma risk, revealing that telomeres carrying TERT promoter mutations were longer than noncarriers." (PMID 35903534, 2022). "Interestingly, mutations in the TERT promoter region were only present in tumors identified as melanoma, and not in benign CTNNB1-mutant melanocytic tumors." (PMID 36077603, 2022). "In melanoma, TERT promoter mutations are the most common mutations in noncoding regulatory regions." (PMID 35903534, 2022). "The Guardant360 NGS ctDNA assay (Guardant Health, Redwood City, CA, USA) includes TERT promoter mutations, but this pan-cancer panel is not adjustable or specifically tailored for melanoma and requires an allele frequency above 0.25% to detect mutations with 100% sensitivity." (PMID 35494035, 2022). "In all three cases, the tumor harbored genomic characteristics typical for melanoma: high mutational load compared to sarcoma samples, an ultraviolet-signature (COSMIC signature 7, C > T nucleotide changes), and typical driver events in the TERT promoter region." (PMID 35053600, 2022). "Interestingly, BRAF was not the most common mutation in the melanoma samples tested by the IMPACT panel but the TERT hot spot promoter mutation appeared with a frequency of 73%." (PMID 34109763, 2021). "Therefore, our study confirmed for the first time that TERT mutation could be used as a predictive marker for anti‐CTLA4 treatment, especially for melanoma." (PMID 32810393, 2020). "Indeed, the effect of TERT promoter mutations on survival seems to be enhanced in melanoma patients that did not carry the polymorphism." (PMID 32784823, 2020). "Furthermore, hereditary melanoma has been associated with germline mutations in high-risk melanoma susceptibility genes (CDKN2A, CDK4, TERT, POT1), polymorphisms in intermediate-risk melanoma susceptibility genes (BAP1, ACD, TERF2IP, MC1R and MITF), and germline missense substitutions in MITF." (PMID 32276436, 2020). "Moreover, TERT expression was exclusive to the melanoma cell lines, either with or without TERTp mutations." (PMID 32267900, 2020). "Due to high GC content of the TERT promoter, and this being a chronologically later mutational hit, we believe BRAF p.V600 and NRAS p.Q61/p.G12 variants to be the best pharmacodynamic biomarkers to monitor treatment response in mutation positive malignant melanoma patients." (PMID 31767937, 2019). "Using thyroid cancer and melanoma cells as cancer cell models that harbored BRAF V600E and TERT promoter mutations, we demonstrated that the BRAF V600E/MAPK pathway promoted the formation and binding of transcriptional GABP complex to the mutated TERT promoter and its activation." (PMID 29422527, 2018). "Out of 20 orthologues of human melanoma-associated loci, 12 contained SNPs with p-values < 10–2 in the MeLiM model, and 6 of them had SNPs reaching a p-value < 10–3: CDKAL1 on SSC7, FTO on SSC6, PLA2G6 on SSC5, TMEM38B-RAD23B on SSC1 and SLC45A2 and TERT on SSC16." (PMID 29963229, 2018). "The newly described gremlin and recurrent somatic mutations in melanoma and other cancers in the TERT promoter, which create de novo E-twenty six/ternary complex factors (Ets/TCF) binding sites, provide an insight into the possible cause of tumor-specific increased TERT expression." (PMID 28726783, 2017).
melanoma (continued). "Since prevalence of both non-nucleolar TERT and TERT promoter mutations correlate with melanoma progression, we investigated whether non-nucleolar TERT might be a marker for these mutations." (PMID 29262649, 2017). "The inclusion of TERT promoter mutations within ctDNA for monitoring would increase the number of patients for whom ctDNA could be used to determine disease status, particularly amongst BRAF and NRAS wild-type melanoma patients." (PMID 29108273, 2017). "In addition, point mutations may create transcription factor binding sites near oncogenes, as has been well-documented at the TERT promoter in melanoma, breast cancer, liver cancer, and other diseases." (PMID 28333948, 2017). "However it is unclear when in melanoma progression TERT and ETS1 proteins are expressed." (PMID 29262649, 2017). "Thus, understanding which of the possible genetic or epigenetic pathways for TERT upregulation correlates with especially high levels of TERT expression in melanoma may facilitate development of more reliable prognostic assays." (PMID 28378855, 2017). "However, ETS1 inhibition induced only a partial reduction of TERT expression suggesting that other transcription factors may be involved in TERT expression in melanoma cells." (PMID 27449293, 2016). "Further, somatic mutations within the TERT promoter, that (similarly to the familial c.−57 T>G variant) create a new ETS transcription factor binding site, occur in a high proportion of melanomas, supporting the important role of telomeres and TERT in melanoma." (PMID 26433962, 2016). "Small numbers preclude a statistical analysis of the numbers of naevi and atypical naevi in POT1 and TERT mutation carriers but the POT1 mutation carriers have a number of atypical naevi in the top 10 % of atypical naevi among our cohort of melanoma cases (data not shown)." (PMID 26433962, 2016). "Other high-risk melanoma genes have been discovered: cyclin-dependent kinase 4 (CDK4), BRCA-1 associated protein (BAP1), and recently via exome sequencing of dense melanoma families, several new high-risk genes affecting telomere functions have been identified: POT1, ACD, TERF2IP and TERT." (PMID 25803691, 2015). "Variants in the TERT-CLPTM1L locus demonstrated pleiotropic effects in opposite directions from other cancers, where the allele previously associated with increased risk of lung and other cancers demonstrated an association with decreased risk of melanoma in our study." (PMID 25789475, 2015). "Additionally, these and similar studies show intra-nevus subclonal heterogeneity—including spatially restricted low-VAF or TERT-promoter mutations—implying that a melanoma may arise from a minor nevus subclone not sampled in routine microdissection." (PMID 41516405, 2026). "Recently, germline variants in genes involved in telomere regulation, including POT1, TERT, ACD, and TERF2IP, have been identified in melanoma-prone families." (PMID 40851494, 2025). "Phosphorylation of FOS, another downstream factor of BRAF V600E, promotes FOS binding to the GABPB 5′ UTR, constantly activating GABPB and promoting its binding to the mutant TERT promoter in PTC cells and melanoma cells." (PMID 38278800, 2024). "In the human melanoma SK-MEL 28 cell line, Akt (also known as protein kinase B) phosphorylates TERT at serine 824 and 277, enhancing telomerase activity." (PMID 38278800, 2024).